IL18 (interleukin 18)
Diseases named in the same sentence as IL18 in open-access papers (continued):
Sharing a sentence is not in itself a finding about the gene and the disease.
COVID-19 (continued). "Finally, we demonstrate that two pro inflammatory cytokines produced by inflammasome activation, IL-18 and IL-1β, do not restrict viral replication and are potential targets to ameliorate pathological inflammation in severe COVID-19." (PMID 39240187, 2024). "The concentrations of several other cytokines also appeared to be increased in the hospitalized COVID-19 patients including IL-8, IL-18, and IFN-γ; however, none of these were statistically significant after adjusting for multiple comparisons (Kruskal–Wallis, P > 0.05)." (PMID 39345212, 2024). "No changes in IL-18 levels have been observed after COVID-19 vaccination." (PMID 36835948, 2023). "Similarly, by comparing IL18+ COVID-19-infected BALF (15.1%) with IL18+ healthy controls, we found host sDEGs but no viral sDEGs." (PMID 37737611, 2023). "However, the presence of inflammasome-related proteins (ASC, IL-1β, IL-18, gasdermin D) in the plasma of severe COVID-19 patients is not always correlated with unfavorable outcomes." (PMID 37508374, 2023). "Most cytokines elevated in COVID-19 are proinflammatory and IL-16 and IL-18 are no exception." (PMID 37398192, 2023). "Moreover, only the cytokine IL-18 was significantly higher between the nonsevere and severe hospitalized COVID-19 cohorts." (PMID 37398192, 2023). "Kidney injury biomarkers, such as functional biomarkers (CysC), damage biomarkers (KIM-1, L-FABP, IL-18, suPAR, and NGAL), and stress biomarkers (TIMP-2 and IGFBP7), appear to be efficient in detecting AKI as well as disease progression in patients with COVID-19." (PMID 35930243, 2022). "Peripheral blood mononuclear cells (PBMCs) derived from severely ill COVID-19 patients display elevated expression of highly active NLRP3 inflammasome, as reflected by abundant levels of cleaved caspase-1 as well as mature IL-1β and IL-18 released upon stimulation in vitro." (PMID 36209522, 2022). "Limiting CRS is especially important for COVID-19 patients, who often display a cytokine storm even in the absence of such therapies, with increased levels of inflammatory cytokines and chemokines (TNF-α, IL-1, IL-6, IL-8, IL-10, IL-18, and MCP-1) that severely damage pulmonary tissue." (PMID 35546150, 2022). "Although serum proinflammatory cytokines (IL6, IL18) were detected in severe cases, we did not observe differences after comparing patients with mild/moderate and severe cases of COVID-19 in multivariate analysis, suggesting that differences do not persist after recovery." (PMID 35172279, 2022). "The “cytokine storm” hypothesis is further supported by our findings given that an increased level of two powerful pro-inflammatory cytokines, IL-1α and IL-18, were found in fatal, not in non-fatal, COVID-19." (PMID 35386707, 2022). "Interestingly, NETosis was also shown to activate pyroptosis, through induction of NLRP3, suggesting that during COVID-19 NETosing neutrophils might also contribute to IL1-β and IL-18 secretion." (PMID 35244141, 2022). "A recent study demonstrated that male COVID-19 patients had higher plasma levels of innate immune cytokines, such as IL-8 and IL-18, along with more robust induction of non-classical monocytes, suggesting that sex difference is a major factor affecting the activation of NLRP3 inflammasome." (PMID 34150848, 2021). "Although the regulation of IL-18 signaling may be a potential therapeutic target for COVID-19, the suppression of IL-18 signaling alone may not be sufficient to control the disease, as many cytokines are involved in the severity of COVID-19." (PMID 33732720, 2021). "Data from these studies suggest that blocking IL-1R7 could be a potential therapeutic strategy to specifically modulate IL-18 signaling and IL-18-related inflammatory diseases including MAS and possibly in patients with MAS-like clinical manifestations of COVID-19." (PMID 33823154, 2021).
COVID-19 (continued). "Importantly, the cytokine profile described in COVID-19-Patients shows large similarities with the cytokine profile of α7nAChRs dysregulated macrophages i.e. massively secreting IL-1β, IL-6, tumor necrosis factor alpha (TNF α) α and IL-18 among others." (PMID 33510335, 2021). "Particularly, the CRS-related cytokines, including IL-6, IL-1β, IL-10, IL-18, and IFN-γ, displayed progressive increase along disease severity from healthy controls to mild and severe patients, highlighting the broad and strong inflammatory responses in severe COVID-19 patients." (PMID 33712622, 2021). "The ROC analysis of the putative biomarkers revealed that IL-18 levels at the cut-off value 190.5pg/mL had the highest discriminative power with AUC of 0.948, the sensitivity of 91.3%, specificity of 95.8%, and an accuracy of 91.5% for differentiating active AOSD from severe COVID-19." (PMID 34367188, 2021). "First, we studied the circulating levels of IL-1α, IL-1β, IL-18, IL-15, IL-12p40, IL-12p70, IL-6, IL-27, IL-1Ra, IL-1RI, IL-1RII, IL-6R and sgp130, which are innate proinflammatory cytokines, and their receptors in survivors and non-survivors of severe COVID-19 and healthy controls." (PMID 36142255, 2022). "Importantly, patients with severe COVID-19 show conspicuous increases in cytokines, including interleukin (IL)-6, monocyte chemoattractant protein (MCP)-1, IL-8, tumor necrosis factor (TNF)-α, IL-1, IL-18, and IL-17, with characteristics of the cytokine storm (CS)." (PMID 36147356, 2022). "Levels of SLAMF1, CCL25, IL2RB, IL10RA, IL15RA, IL18 and CST5 were significantly upregulated in patients with critical COVID-19 illness compared to individuals negative for COVID-19." (PMID 40475767, 2025). "Some pro-inflammatory cytokines and chemokines, such as IL-6, IL-1, IL-18, and TNF-α, have been detected in high levels in patients with severe COVID-19 compared to non-severe cases." (PMID 39504070, 2024). "There is evidence that the level of IL-18 in COVID-19 patients with MAS and ARDS is significantly higher than that in patients without MAS and ARDS, and high levels of IL-18 and IL-1Ra also seem to be related to the mortality of patients." (PMID 37483597, 2023). "In Non-SOT COVID-19 patients, we observed 6 (IL-13, IL-10, IFN-γ, IL-12p70, MCP-2, IL-6) and 9 (IL-16, IL-13, TNF-α, IL-6, IL-18, IL-15, MIP-1α, IL-2Ra, IL-8) cytokine correlations with monocyte and neutrophil derived cfDNA, respectively." (PMID 35075453, 2022). "While the levels of IP-10, IL-15 and IL-18 were exclusively increased in SOTRs with COVID-19, Non-SOT patients with COVID-19 showed solely higher levels of IFN-β, IL-2, IL-10, GM-CSF and low levels of Eotaxin, MCP-1, MIP-1β, IL-4, IL-5." (PMID 35075453, 2022). "Clustering of IL-18, IP-10, MCP-1 and MIP-2α characterized patients in acute-phase COVID-19 without bacterial superinfections." (PMID 35007290, 2022). "Five COVID-19 ICU patients (DRASTIC-011, −012, −013, −021, −023) had no detectable cytokines across 13 cytokines/chemokines, while high IL-18 levels were detected in plasma of DRASTIC-011, −012, −013- and − 023 patients." (PMID 34462740, 2021). "IL-6 and IL-18, among others, were elevated in ICU status COVID-19 patients versus non-ICU COVID-19 patients and hospitalized controls." (PMID 34960684, 2021). "We detected increases in IL-18, IL-6, and MIP-1α in the COVID-19 ICU group versus controls and the non-ICU group (FDR < 0.05)." (PMID 34960684, 2021). "Noteworthy, the fold change of IL-18 in patients with active AOSD was approximately 594, which was much higher than that in severe COVID-19 (Fold change 2.17), without statistical comparability." (PMID 33552062, 2020). "However, in the plasma of SARS-CoV-2-infected patients we found increased levels of both axes, IL-6/CRP and IL-18/ferritin; however, although IL-6 positively correlated with CRP, IL-18 failed to correlate with ferritin in COVID-19 patients." (PMID 35663992, 2022).
COVID-19 (continued). "Interestingly, a great increase in plasma levels of IL-18, a cytokine involved in the induction of the CD4+ TH1 profile, was observed in children with severe but not in those with non-severe COVID-19 (p<0.0001)." (PMID 35663467, 2022). "Similarly, Eotaxin (p=0.080), IL-10 (p=0.095), IL-18 (p=0.095) and IL-2Ra (p=0.071) were higher and IFN-β (p=0.094) was lower in Non-SOT COVID-19 patients (FDR<0.26 for all)." (PMID 35075453, 2022). "The increase in COVID-19 severity and C-reactive protein concentration positively correlated with increased concentration of the P2X7 receptor in the plasma, but not with the IL-18 cytokine." (PMID 35663992, 2022). "For instance, patient DRASTIC-063 displayed higher IFN-2, IL-10, IL-12p70 and IL-17A in ETA (d8) than other COVID-19 respiratory samples, while the plasma (d7) level of IFN-2 was also higher, DRASTIC-063 had higher plasma level of IL-18 but not IL-10, IL-12p70 or IL-17A." (PMID 34462740, 2021). "In addition, we found that calcium levels are reduced in severe COVID-19 patients, and this parameter showed strong negative correlations with MCP-1, IL-18, IL-8, IL-6, and IL-10 and positive correlation with T cell number, indicating its good prognostic factor." (PMID 33692788, 2021).
colitis (279 papers, 2009 to 2026). Inflammation of the colon. "Previous works have implicated intestinal IL-18 signaling in the maintenance of gut epithelial integrity in the context of colitis." (PMID 41480237, 2026). "XXLP significantly improved colitis symptoms, including weight loss and colon shortening, and reduced the concentrations of inflammatory markers IL-1β, IL-18, TNF-α, and IL-6." (PMID 41901297, 2026). "Previous works have implicated IL-18 in the homeostatic crosstalk between the intestinal epithelium and gut bacteria, in particular in the context of colitis and inflammatory bowel disease." (PMID 41480237, 2026). "Mice treated with fucoidan exhibited significant protection from colitis, evidenced by longer colonic length, less weight loss, and lower expression levels of inflammatory genes such as Il‐1b, Il‐18, Il‐6, Nos2, and Tnfα." (PMID 40545965, 2025). "Excessive IL-18 production, as observed in conditions involving the deletion of IL-18BP or colitis, has been linked to the loss of mucus-producing goblet cells." (PMID 41116055, 2025). "Mice harboring the NLRC4 T337S mutation exhibit elevated serum IL-18 and canonical inflammasome activation (via Pycard, Casp1, and Gsdmd) in IECs but fail to develop spontaneous colitis or systemic inflammation, even upon immune challenge." (PMID 41116055, 2025). "Recent investigations have underscored the pivotal role of unchecked NLRP3 inflammasome activation in the development of inflammatory bowel disease, with heightened secretion of mature IL-1β and IL-18 linked to exacerbated colitis." (PMID 40640149, 2025). "Another IL-1 family cytokine IL-18 has been implicated in inducing colitis by limiting goblet cell differentiation." (PMID 38376154, 2024). "Among them, the NLRP3 pathway has been shown to activate GSDMD in a mouse model of colitis-associated colon cancer and mediate the release of IL-1β and IL-18." (PMID 38898209, 2024). "Increased NFκB and decreased IL18 expression also contributed to the progression of colitis and CAC tumorigenesis in Casp-1- and Casp-12-deficient animals." (PMID 38892354, 2024). "This cytokine is known to produce a protective effect against enterocyte inflammation and colitis, which is supported by the susceptibility of IL-18 knockout mice and IL-18 receptor knockout mice to colitis." (PMID 36986124, 2023). "From these factors, RNA expression of Bax, Hdac4, IL-18, Casp8 and Hif1 returned to baseline level compared to the colitis- associated upregulation, when MMs were depleted with l-clodronate during DSS-treatment." (PMID 38105266, 2023). "Mice with NLRP3, ASC, or caspase-1 gene knockout are more susceptible to DSS-induced colitis, which is a result of reduced IL-18, a downstream component of the NLRP3 inflammasome." (PMID 37370025, 2023). "The expression of Hdac4, IL-18 and Casp8 showed a trend similar to Bax’s, where colitis-associated overexpression was diminished in the case of concurrent l-clodronate administration." (PMID 38105266, 2023). "AIM2-deficient mice showed reduced production of IL-1β and IL-18, but infusion of IL-18 alleviated the higher colonic burden of E. coli and susceptibility to colitis." (PMID 37191444, 2023). "Implicated in colitis through reduction in short-chain fatty acids and the anti-inflammatory IL-18 in mice." (PMID 36341463, 2022). "On the other hand, activation of IL-18 signaling exaggerated the progression of DSS-induced colitis associated with the depletion of goblet cells." (PMID 36552612, 2022). "Following Citrobacter rodentium infection, CYLD-deficient mice exhibit a substantially higher IL-18 concentration, indicating that severe mice colitis depends on elevated IL-18 production." (PMID 35145062, 2022). "The family Rikenellaceae has been recognized as protective bacteria in colitis and are inversely associated with pro-inflammatory cytokine IL-18." (PMID 35741945, 2022).
colitis (continued). "Excessive IL-18 signaling through genetic deletion of IL-18BP resulted in loss of mature mucus-producing goblet cells associated with colitis." (PMID 36313762, 2022). "ATG16L1 deficiency in hematopoietic or myeloid cells renders mice more susceptible to experimental colitis due to hyperactivation of pan inflammatory responses including the inflammasome and IL1β/IL18 processing." (PMID 37425656, 2022). "IL-18 is a proinflammatory interleukin matured by NLRP3 inflammasome activation, and IL-18 equilibrium in the epithelium has been implicated in barrier function in colitis, where IL-18 coordinates goblet cell maturation transcriptional programs." (PMID 36145301, 2022). "High serum levels of IL-18 are associated with intestinal inflammation and transgenic mice are more prone to colitis, while IL-18 inhibition is protective in models of inflammatory bowel disease (IBS)." (PMID 36613465, 2022). "Prevotella intestinalis is another member of the family implicated in intestinal inflammation and particularly colitis through a reduction in SCFAs and the anti-inflammatory interleukin IL-18 in mice." (PMID 36341463, 2022). "On the other hand, caspase-1 (a key inflammasome component) deficiency resulted in limited IL-1β and IL-18 production associated with ameliorated inflammation in DSS-induced colitis." (PMID 33562334, 2021). "Our data are supported by evidence demonstrating protection against experimental colitis, minimizing mucosal damage and maintaining the epithelium equilibrium in IL-18 deficient mice." (PMID 33535452, 2021). "We found that the concentration of IL-18 in colon tissue homogenate or culture colon explant supernatant was significantly reduced in Gsdmd-deficient mice during colitis." (PMID 34721422, 2021). "Previously, the expression levels of mRNA encoding inflammasome components were analyzed in a murine model of colitis and significantly lower levels of inflammasome-encoding gene expression including IL18 and NLRP3 were found in response to PDE4 inhibition." (PMID 34884681, 2021). "Nonetheless, a strict equilibrium of the IL-18 level is important for epithelial integrity as overexpression of IL-18 in this compartment leads to a loss of matured goblet cells and increased susceptibility to experimental colitis." (PMID 33435303, 2021). "Clinical studies reveal that blocking IL-18 with IL-18BP reduces the severe life-threatening colitis in children with the NLRC4 mutation." (PMID 33823154, 2021). "Together, our data suggest that GSDMD promotes IL-18 release during colitis; and that the released IL-18 mediates colitis development by promoting goblet cell loss." (PMID 34721422, 2021). "Cohousing of mice that were unable to produce IL-18 with normal mice limited colitis in knock-out mice, underlying an important role of microbiome dysbiosis in inflammation-induced colorectal cancer." (PMID 33255437, 2020). "Over the last ten years, it has been demonstrated that the development of experimental UC-like colitis increases intestinal permeability, loss of TJ proteins is associated with an upregulation of pro-inflammatory cytokines (IL-18)." (PMID 33121008, 2020). "It was reported that the occurrence of colitis is associated with the secretion of IL-1β and IL-18, our data also demonstrated that secretion of IL-1β and IL-18 increased in colitis mice colon." (PMID 33240089, 2020). "Sensing of commensal gut fungi through the Card9–Syk signaling axis promotes inflammasome activation and maturation of IL-18, which plays a protective role in colitis and colitis-associated carcinogenesis." (PMID 32550001, 2020). "In agreement with an important role for IL-18 in protection against colitis-associated tumorigenesis, colons of IL-18−/− mice contained significantly more tumors than the treated wild-type mice." (PMID 33294056, 2020).